SOSTDC1 (sclerostin domain containing 1)
Diseases named in the same sentence as SOSTDC1 in open-access papers (continued):
Sharing a sentence is not in itself a finding about the gene and the disease.
prostate carcinoma (4 papers, 2016 to 2023). A carcinoma that arises from epithelial cells of the prostate gland. "Hepcidin synthesis in prostate cancer cells is regulated by Wnt- and SOSTDC1-associated pathways." (PMID 33868231, 2021). "A unique confluence of pathways, including BMP4/7, IL6, Wnt, and the dual BMP and Wnt antagonist SOSTDC1, regulates the synthesis of hepcidin in prostate cancer." (PMID 36895478, 2023). "For example, previous reports have shown hyper-methylation in SOSTDC1 promoter CpGs and epigenetic silencing of SOSTDC1 transcription via increased methylation in prostate cancer." (PMID 27087917, 2016). "Interestingly in prostate cancer the SOSTDC1 gene promoter is highly methylated leading to suppression of gene transcription, and this is associated with increased HAMP expression and poorer prognosis in patients with prostate tumours." (PMID 29771984, 2018).
Wilms tumor (4 papers, 2010 to 2022). An embryonal neoplasm characterized by the presence of epithelial, mesenchymal, and blastema components. "Within the Oncomine database, we found that SOSTDC1 levels were reduced in adult renal clear cell tumors and pediatric Wilms tumors." (PMID 21080955, 2010). "We investigated the frequency of LOH within the SOSTDC1 gene in pediatric Wilms tumors and adult renal tumors." (PMID 21080955, 2010). "Evidence from Wilms tumors has narrowed the region of interest on chromosome 7 to a 2-Mb region within 7p21 that contains ten known genes, including SOSTDC1." (PMID 21080955, 2010). "In Wilms tumor, SOSTDC1 has been identified as a candidate tumor suppressor gene, which may have a role in the progression of tumorigenesis." (PMID 26378658, 2015). "To investigate this hypothesis, we interrogated the Oncomine database to examine the SOSTDC1 levels in adult renal clear cell tumors and pediatric Wilms tumors." (PMID 21080955, 2010). "Overall, we observed LOH at the SOSTDC1 gene in 4/25 (16%) of Wilms tumor patients." (PMID 21080955, 2010). "The median value of SOSTDC1 expression in normal adult tissue was 1.13 and that in normal fetal tissue was 4.00, while the levels of SOSTDC1 expression in adult renal clear cell carcinoma and pediatric Wilms tumors were significantly lower, at -1.00 and -2.92, respectively (p < 0.001)." (PMID 21080955, 2010). "When adult renal cell carcinoma samples were investigated for LOH within SOSTDC1, we found that LOH was present in five of 36 adult renal carcinoma samples and four of 25 Wilms tumors." (PMID 21080955, 2010). "We hypothesized that SOSTDC1 LOH might lead to decreased protein expression in the RCC and Wilms tumor samples." (PMID 21080955, 2010). "In Wilms tumors, a consensus region of LOH has been identified within 7p21 containing ten known genes, including two candidate tumor suppressor genes, mesenchyme homeobox 2 (MEOX2) and sclerostin domain containing 1 (SOSTDC1)." (PMID 21080955, 2010).
renal carcinoma (3 papers, 2010 to 2022). A carcinoma arising from the epithelium of the renal parenchyma or the renal pelvis. "We observed within an analysis of the Oncomine database that SOSTDC1 is expressed in normal renal tissue and that its expression is decreased in adult and pediatric renal cancer." (PMID 21080955, 2010). "Future experiments that investigate alternative regulatory mechanisms such as epigenetic silencing of SOSTDC1 may uncover more pertinent contributors to the reduced SOSTDC1 protein levels observed in renal cancer." (PMID 21080955, 2010). "Although our conclusions are limited by sample size, we suggest that an alternative mechanism such as epigenetic silencing of SOSTDC1 may be a key contributor to the reduced SOSTDC1 mRNA and protein levels observed in renal cancer." (PMID 21080955, 2010). "We had previously observed that SOSTDC1 expression is decreased in adult renal carcinomas." (PMID 21080955, 2010). "Notably, Sostdc1 expression was upregulated in normal kidneys but downregulated in renal cancer." (PMID 36338475, 2022). "Moreover, down-regulation of SOSTDC1 was observed in renal cancer, and SOSTDC1 could suppress the proliferation of renal cancer cells via regulating BMP and Wnt3a signaling." (PMID 27087917, 2016). "This study shows that genetic aberrations near SOSTDC1 are not uncommon in renal cancer, and occur in adult as well as pediatric renal tumors." (PMID 21080955, 2010). "Previous findings demonstrated that SOSTDC1 is abundantly expressed in the renal epithelia of the distal tubules, collecting ducts, and urothelium and that it is downregulated in adult renal carcinomas; however, the association between LOH at SOSTDC1 and adult renal cancer has not been explored." (PMID 21080955, 2010). "Adult renal carcinoma samples with and without LOH at SOSTDC1 were also examined for changes in Wnt signaling via immunohistochemistry." (PMID 21080955, 2010).
acute myeloid leukaemia (2 papers, 2022 to 2024). "SOSTDC1 restrains the proliferative ability by promoting the apoptotic rate in acute myeloid leukemia." (PMID 39202425, 2024). "Sostdc1 also increased the cell apoptotic rate and inhibited the proliferative ability in acute myeloid leukaemia (AML) by suppressing the Wnt/β-catenin pathway." (PMID 36338475, 2022).
Alport syndrome (2 papers, 2021 to 2022). A rare renal disease characterized by glomerular nephropathy with hematuria progressing to end-stage renal disease (ESRD), frequently associated with sensorineural deafness, and occasionally with ocular anomalies. "Deletion of Sostdc1 gene in mice resulted in supernumerary teeth and improved the loss of renal function in Alport syndrome." (PMID 36338475, 2022). "Deletion of the Sostdc1 gene in mice resulted in supernumerary teeth, and improved the loss of renal function in Alport syndrome." (PMID 36338475, 2022).
breast tumor (2 papers, 2022 to 2024). "In addition, bioinformatics analysis results had confirmed that SOSTDC1 expression was higher in BRCA1‐mutant breast tumor patients." (PMID 38864559, 2024). "In addition, our previous study reported that SOSTDC1 is downregulated in 98.1% of breast tumour tissues and it coincides with DNA methylation of CpG sites in promoter region of SOSTDC136." (PMID 34997107, 2022).
multiple myeloma (2 papers, 2019 to 2022). "The distribution of Sostdc1 staining in bones infiltrated with 5TGM1 myeloma cells in vivo suggested its presence in both myeloma and osteoblast lineage populations when in close proximity." (PMID 30776499, 2019). "In conclusion, we have shown that Sostdc1 is a potent suppressor of OB differentiation in vitro and that the production of this protein in OBs and myeloma cells is induced when these cells interact with each other." (PMID 30776499, 2019). "However, our in vitro studies showed that myeloma cells produced very low levels of Sostdc1 and the protein is undetectable in OB progenitor cells, when these cells are grown alone." (PMID 30776499, 2019). "Together, these findings suggest that Sostdc1 expression in 5TGM1-infiltrated bones as a result of the interaction between myeloma and osteoblast lineage populations, could result in suppression of osteoblast differentiation." (PMID 30776499, 2019). "Our studies, using a murine model of MM, show that Sostdc1 is present in the bone marrow of tibiae infiltrated with myeloma cells but not in the bone marrow of non-tumour bearing (naïve)." (PMID 30776499, 2019). "As Sostdc1 is a putative inhibitor of OB differentiation that is not expressed in adult bone, its presence in MM cells and in myeloma-infiltrated bones would make it an interesting candidate in the context of myeloma-induced bone disease." (PMID 30776499, 2019). "•Sostdc1 is present in myeloma-infiltrated bone disease and not present in normal bone." (PMID 30776499, 2019). "Our initial hypothesis was that Sostdc1 was produced by myeloma cells and not by OB lineage cells." (PMID 30776499, 2019).
prostate tumours (2 papers, 2018 to 2022). "In prostate tumours, the Sostdc1 promoter was hypermethylated in prostate tumours, leading to the suppression of hepcidin secretion due to attenuation of BMP4/7-mediated Smad phosphorylation, resulting in inhibition of cell survival." (PMID 36338475, 2022).
viral infection (2 papers, 2020 to 2021). "Recent study using SOSTDC1-reporter mice identified a potential regulatory role for Tfh-secreted SOSTDC1 in promoting the development of regulatory follicular T cells in germinal centers following viral infection or immunization." (PMID 33322152, 2020).
adenoma (1 paper, 2015). A neoplasm arising from the epithelium. "The expression level of SOSTDC1 protein in thyroid malignant lesions was significantly decreased as compared with that in benign lesions (goiters and adenomas)." (PMID 26378658, 2015).
Autoimmunity (1 paper, 2021). The occurrence of an immune reaction against the organism's own cells or tissues. "Functional differences within TFR, TFH, and Sostdc1+ TFH cells, rather than differences in the relative frequencies of these subsets, are therefore likely responsible for the autoimmunity observed in our mixed chimera model of autoantibody-mediated disease." (PMID 34795279, 2021).
benign prostatic hyperplasia (1 paper, 2017). A non-cancerous nodular enlargement of the prostate gland. "At last, we verified five methylated sites (cg06363129, cg07220448, cg11417025 in SOSTDC1; cg08843517 in CYBA; and cg05385513 in EFEMP1) in PCa and normal tissues, including adjacent tissues and benign prostatic hyperplasia (BPH) through pyrosequencing." (PMID 28938548, 2017).
demyelination (1 paper, 2018). "Since Sostdc1 is produced exclusively by activated astrocytes within the non-VN lesion area during the period of first 10 days post demyelination our data corroborate with the long-postulated notion that astrocytes are one of the key regulators of OPC differentiation fate." (PMID 30222103, 2018).
hair loss (1 paper, 2022). "Taken together, LVs may contribute to the stimulation of HF growth through Sostdc1 secretion, indicating a potential therapeutic strategy for the treatment of hair loss." (PMID 35678675, 2022). "Taken together, our results reveal that LVs may stimulate HF growth through Sostdc1 secretion, indicating a potential therapeutic strategy for the treatment of hair loss." (PMID 35678675, 2022).
infertile (1 paper, 2019). "Sostdc1 expressing F1 generation adult males (n = 5) were found to be infertile when mated with normal mature WT females (n = 10) for more than three months (for each individual mating set)." (PMID 31391487, 2019).
kidney cancer (1 paper, 2010). Primary or metastatic malignant neoplasm involving the kidney. "Improper splicing, a mechanism that contributes to dysregulation of the Wilms tumor suppressor gene WT1, might also contribute to the observed downregulation of SOSTDC1 in kidney cancer." (PMID 21080955, 2010). "To assess whether expression levels of SOSTDC1 were similarly decreased in pediatric kidney cancer patients, we queried the Oncomine database." (PMID 21080955, 2010).
kidney tumors (1 paper, 2010). "We then performed single nucleotide polymorphism (SNP) and sequencing analyses of SOSTDC1 in 25 pediatric and 36 adult renal tumors." (PMID 21080955, 2010). "When tumor samples were stained for SOSTDC1, the protein showed defined perinuclear and diffuse cytosolic localization in both adult and pediatric renal tumors." (PMID 21080955, 2010). "This study investigates the role of SOSTDC1, a candidate renal tumor suppressor gene, in adult and pediatric renal tumors." (PMID 21080955, 2010). "The sample size and expression sensitivity of this method improved the likelihood of detecting a notable change in SOSTDC1 that correlated with development of renal tumors." (PMID 21080955, 2010). "Although our limited sample size does not allow us to definitively refute the hypothesis that LOH is the primary regulator of SOSTDC1 in pediatric and adult renal tumors, we suggest that other modes of regulation must also be considered." (PMID 21080955, 2010). "The capacity for SOSTDC1 to regulate two key signaling pathways, BMP and Wnt, in renal cells make it of particular interest as a potential renal tumor suppressor." (PMID 21080955, 2010). "The observations that LOH at SOSTDC1 did not decrease SOSTDC1 protein expression or increase Wnt-induced signaling suggest that LOH may not be the key regulator of SOSTDC1 protein expression in pediatric and adult renal tumors." (PMID 21080955, 2010).
male infertility (1 paper, 2019). The inability of the male to effect fertilization of an ovum after a specified period of unprotected intercourse. "Therefore, these two different observations from independent sources collectively established a probable correlation between high Sostdc1 expression and activated phospho smad 1/5/8 signaling with human male infertility, supporting our present findings in Tg rats." (PMID 31391487, 2019). "Additionally, this study further established the importance of Sostdc1 in unresolved cases of certain forms of idiopathic male infertility where failure of the natural down-regulation of Sosdc1 during puberty, may be one of the reason of insufficient sperm production." (PMID 31391487, 2019).
metastatic prostate carcinoma (1 paper, 2023). A carcinoma that arises from the prostate gland and has spread to other anatomic sites. "Unlike ligands, soluble antagonists in metastatic prostate cancer patients are consistently increased in patients with CHRD at 12%, NOGGIN, SOSTDC1, FSTL1 at 7% and GREM2 at 6% of patients." (PMID 36054271, 2023).
myelomeningocele (1 paper, 2020). Myelomeningocele is the most severe form of spina bifida. "SOSTDC1 on chromosome 7, which codes for sclerostin domain-containing protein 1, associated with myelomeningocele in the EA population." (PMID 32970752, 2020). "In mouse tooth development, the homolog Sostdc1 serves as an inhibitor of Lrp5/6-mediated Wnt signaling, but SOSTDC1 has not previously been associated with myelomeningocele." (PMID 32970752, 2020).
neuropathy (1 paper, 2022). A disorder affecting the nervous system that manifests with pain, tingling, numbness, and/or muscle weakness. "Dead M. leprae increased the expression of WNK, IFNB, IKBKA, and HLA-DQA1 (genes related to neuropathy), in addition to GJA1 and RAF1 (for Schwann cell reprogramming) and KCNJ10, OLIG1, SHH, and SOSTDC1 (for neural regeneration)." (PMID 35492305, 2022).
Peri-Implantitis (1 paper, 2022). An inflammatory process with loss of supporting bone in the tissues surrounding functioning DENTAL IMPLANTS. "MAPT, GZMK, and SOSTDC1 were highly correlated with high abundance of immune cells, possibly reflecting immune cell perturbations accompany ageing-associated signalling pathways to play a role in peri-implantitis lesions in aged tissues." (PMID 36267464, 2022).
pituitary adenomas (1 paper, 2015). "A review of 13 whole genome approaches in pituitary tumors with the goal of identifying Wnt family inhibitors showed that expression of WF1, SFRP2, FRZB, SFRP4, DKK2, and SOSTDC1 genes is decreased in pituitary adenomas compared to normal pituitary tissue, while that of SFRP1 and SFRP4 is increased." (PMID 25834571, 2015).
renal oncocytoma (1 paper, 2024). "Expression of biomarkers MAPRE3, ADGRF5, and GPNMB differentiates renal oncocytoma from chromophobe RCC, and PIGR and SOSTDC1 distinguish papillary RCC from MTSCC." (PMID 38703764, 2024).
skin cancer (1 paper, 2018). "Even going beyond, SOSTDC1 and MYO15A have not been previously reported as skin cancer biomarkers." (PMID 29750795, 2018). "The vast heterogeneity of the sample collection with respect to diverse factors like platforms, origin, parts of the body, etc. positively influenced in the finding of 6 genes that had not previously related to skin cancer: SCGB2A1, CRYBA2, ANXA3, PCP4, SOSTDC1 and MYO15A." (PMID 29750795, 2018).
thyroid (1 paper, 2015). "Taken together, these results indicate that SOSTDC1 may inhibit thyroid tumorigenesis, at least partly, through regulating the Rb-E2F pathway." (PMID 26378658, 2015).
thyroid tumor (1 paper, 2015). A benign or malignant neoplasm affecting the thyroid gland. "In agreement with the TCGA data, the expression levels of SOSTDC1 were significantly decreased in most thyroid tumor tissues in comparison with those in adjacent non-tumorous thyroid tissues." (PMID 26378658, 2015).